CD163 (CD163 molecule)
Diseases named in the same sentence as CD163 in open-access papers (continued):
Sharing a sentence is not in itself a finding about the gene and the disease.
infection (continued). "During the neonatal period, high expression of CD163 in both M1 and M2 macrophages could be relevant, since newborn infants have an elevated turnover of erythrocytes under physiologic conditions and are prone to hemolysis during infection." (PMID 30050534, 2018). "CD163 has important biological functions, and the complete knockout could have a negative physiological impact on the animal, particularly with respect to the inflammation response and/or infection by other pathogens." (PMID 29925651, 2018). "The models informed by our data support the hypothesis that although CD163 may have enhanced cell susceptibility, it was not essential for productive infection in our study." (PMID 27770812, 2016). "The objectives of this study were to investigate associations between numbers of CD163 and CD169 positive macrophages, cathepsin positive areolae, and type 2 PRRSV load at the maternal–fetal interface in order to examine important factors related to transplacental infection." (PMID 27494990, 2016). "However, the percentage of CD163 positive cells was found significantly lower at 18 hpi compared to 0 hpi, thus indicating potential shedding or form change in the CD163 receptor within the 18 h infection period." (PMID 27770812, 2016). "Thus according to model B, prior to infection (or during mock infections) PAMs can be classed into four categories: CD163 negative and non-susceptible, CD163 positive and non-susceptible, CD163 negative and susceptible, and CD163 positive and susceptible." (PMID 27770812, 2016). "In order to determine if expression of porcine CD163 on the surface of cell lines not expressing CD163 could increase their susceptibility to infection by ASFV we constructed cells lines stably expressing CD163." (PMID 24398227, 2014). "After 24 hours of induction, some gene have slightly change, such as CD163 elevated by ST169 (H1N1) (2.37), and IL-10 elevated by HKG9 (H9N2) (2.63), whereas, most of the M1/M2 markers return to the normal level, it seems that influenza virus caused AM immunosuppression after 24 hours infection." (PMID 25105760, 2014). "A big drawback of the clustering of CD163+ cells is that the migrating monocytic cells may leave “open doors” for other upper respiratory pathogens to invade through the mucosa, establish a secondary infection and enhance the severity of the disease." (PMID 24007551, 2013). "Together with that of HP, elevation of CD163 (CD163 antigen, 4.6-fold) suggests that intracellular signalling leading to increased hemoxygenease activity and the release of anti-inflammatory cytokines may have occurred after infection." (PMID 19196461, 2009). "In an ambitious paradigm of multiplex gene editing, we generated pigs carrying concurrent edits in CD163, SIGLEC1, and ANPEP, thereby endowing the animals with compounded resistance to multiple infections." (PMID 39943192, 2025). "In contrast to the decrease in CD4+ T cells, CD8+ T cells, and CD19+ B cells, there was a significant increase in the number of CD163+ macrophages and CD56+ NK cells in the peripheral lymphoid organs upon the infection." (PMID 40143222, 2025). "The 25, 50 and 100 mg/kg of baicalin diminished CD163 mRNA expression and increased the TWEAK mRNA expression level from the blood vessels compared to the infection group (p < 0.001)." (PMID 40427615, 2025). "To evaluate the influence of CD163 downregulation by tilmicosin on PRRSV entry, we detected the effects of 150 μg/ml tilmicosin pretreatment (12 h before infection) on PRRSV entry and replication from 0 h to 10 h." (PMID 40952173, 2025). "By 12 dpi and infection resolution, fLX display residual iMO and are enriched in CD4 + PIM and CD163 + CD206 + IM." (PMID 40920821, 2025). "The surface-exposed GaPR of Lev-GaPR-PCN selectively binds to overexpressed CD163 and LRP1 receptors on MRSA-infected cells after forming complexes with infection site-enriched secreted Hpg and Hpx, allowing efficient entry into infected cells." (PMID 40963910, 2025).
infection (continued). "GaPR-PCN exhibited excellent binding ability with host-derived heme-binding proteins (Hpx/LRP1 and Hpg/CD163) and the iron-regulated surface determinant (Isd) system of MRSA for infection site, infected cell, and intracellular targeting." (PMID 40963910, 2025). "Our analysis revealed that both cell types express CD163 and CD169, the key molecules involved in infection." (PMID 39723134, 2024). "Our approach is based on the detection in isolated hemocytes from G. mellonella hemolymph of cell membrane markers typically expressed by human immune cells upon inflammation and infection, for instance CD14, CD44, CD80, CD163 and CD200." (PMID 38191588, 2024). "After infection with S. epidermidis 1457, macrophages predominantly shifted to CD163+/CD200R1+ (CD163+: 66.84% ± 4.95." (PMID 39567551, 2024). "The observed stability of cardiac CD163 expression across phenotypic groups, in conjunction with significant viral load in the highly infected fetuses, suggests that the population of susceptible cells was present prior to infection and is not the product of macrophage infiltration." (PMID 38389522, 2024). "Cell membrane markers typically expressed on monocytes/macrophages upon inflammation/infection (CD14, CD44, CD200), M1-polarization (CD80) and M2-polarization (CD163) were analyzed in the hemocyte population isolated." (PMID 38191588, 2024). "Compared with the EBV-HLH and HLH-other infection group, FCGR2A and CD163 were significantly increased in the HLH-malignancy group." (PMID 37653176, 2023). "Elevated expression of multiple inflammatory genes, including IL6, TNF, IL10, and IL1B, were observed in the CD163+MRC1+TREM2 Mac and CD163+MRC1− subsets in both Cohort 1 and 2 after infection." (PMID 37024448, 2023). "Compared with the HLH-malignancy group, three DEPs were significantly decreased in the HLH-other infection group, including CD32 (FCGR2A), CD163, and polymeric immunoglobulin receptor (PIGR)." (PMID 37653176, 2023). "It has been reported that host cell surface proteins, such as CD163, mediate PRRSV infection, and CD163 knockout pigs show resistance to PRRSV infection, indicating blocking PRRSV entry can be a promising strategy to prevent the infection." (PMID 37609059, 2023). "Our previous study found that recombinant PRRSV-2 antigen A1 stimulated the repolarization of M2 PAMs to M1, leading to a reduction in CD163 expression that provided broad protection against PRRSV-1 and PRRSV-2 strain infection." (PMID 36992483, 2023). "We also compared the infections of two rescued JSTZ1712-12 PRRSV2 carrying fluorescent proteins (rJSTZ1712-12-EGFP and rJSTZ1712-12-dsRed) in CD163-3D4/21 cells." (PMID 36146862, 2022). "Studies have shown that pigs lacking the CD163 cell receptor or cysteine-rich scavenger receptor domain 5 (SRCR5) of CD163 are resistant to both PRRSV-1 and PRRSV-2 infections." (PMID 35681845, 2022). "The expression of CD11b, CD4, CD14, and CD68 for M0; IL-6, HLA/DRA, and CXCL10 for M21, and IL-10, CD163, fibronectin-1 or FN1, and CCL17 was evaluated by qPCR at 2 and 24 h after infection." (PMID 35889103, 2022). "The results showed that the levels of the M1-type membrane molecules CD80 and CD86 were increased on human dMφ after infection with T. gondii, while the levels of the M2-type membrane molecules CD206 and CD163 were decreased." (PMID 36514159, 2022). "We next examined the infections of two rescued PRRSV2 carrying fluorescent proteins (rXJ17-5-EGFP and rXJ17-5-dsRed) in CD163-3D4/21 cells." (PMID 36146862, 2022). "Few changes in myeloid cell proportions were observed following ZIKV-infection, although CD14+ CD163– CD206– cells were higher in the decidua of uninfected macaques compared to ZIKV-infected macaques (22.0 ± 13.1% and 8.5 ± 6.4%, respectively, p = 0.025)." (PMID 34394129, 2021).
infection (continued). "The initial decrease of CD163-positive cells is likely due to virus growth and cell death, and the recovery of CD163-positive cells may be due to the induction of CD163 expression in immature cells, the recruitment of CD163-positive cells to infection sites, or both." (PMID 33916997, 2021). "CSFV infection led to the emergence of an additional CD163+CD14+ cell population, which showed the highest levels of Alfort-187 and C-strain infection." (PMID 34445493, 2021). "These repolarized M1 PAMs decreased the total expression of CD163 for PRRSV entry, and hence offer a broad protection for both PRRSV-1 and PRRSV-2 strains infection." (PMID 34579246, 2021). "Since CD163 is considered to be a putative receptor for the porcine reproductive and respiratory syndrome virus (PRRSV), the effects of DEX on the infection of IPKM by PRRSV were evaluated." (PMID 33447967, 2021). "Based on the biological features of CD163, healthy pigs with abnormally high CD163 levels due to over-expression or high levels of monocytes may exhibit autoimmune abnormalities, abnormal iron metabolism, or subclinical infections, which could trigger excessive macrophage activation." (PMID 34384354, 2021). "In contrast, STING KO infected mice displayed an enhanced frequency of anti-inflammatory CD163+ and CD206+ macrophages at 4 weeks post-infection in comparison with splenic macrophages from WT infected animals." (PMID 33989349, 2021). "Among others, CD163, a cysteine-rich scavenger receptor (SRCR), acts as the determinant receptor for PRRSV entry and infection." (PMID 32404209, 2020). "The increase in infection by C-HIV with a two fold increase (p=0.009) and CI-HIV with a 1.95 fold increase (p=0.012) compared to F-HIV, was also seen for the CD163+ macrophages in the isolated mucosal immune cells." (PMID 32876566, 2020). "In addition, we wanted to test if plasma levels of CD163 could be used to detect Bb infection." (PMID 33036200, 2020). "CD163 and CD169 play a main role during infection, uncoating of the viral particle, activation of clathrin-mediated endocytosis and release of viral genome in the cytoplasm." (PMID 30842948, 2019). "CD163 SRCR5-edited piglets were generally healthy with normal food and water consumption after infection with PRRSV JXA1 and MY." (PMID 31440241, 2019). "However, the absence of CD163 expression associated to the fact that PFMΦ did not experience depletion upon in vivo infection are in agreement with the occurrence of a viral interaction without productive infection." (PMID 31130951, 2019). "Like Ki67 and PD-1, a significant difference (p ≤ 0.05) for days post infection and treatment status (VEH vs. Δ9-THC) was detected for CD163+ measurements." (PMID 31114576, 2019). "The results of this study show that live pigs carrying a CD163 SRCR5 deletion are healthy and maintain the main biological functions of the protein, whilst the deletion renders target cells of PRRSV resistant to infection with the virus." (PMID 28231264, 2017). "However, as CD163 has important biological functions the complete knockout could have a negative physiological impact on the animal, particularly with respect to inflammation and/or infection by other pathogens." (PMID 28231264, 2017). "Even though CD163 has been proposed as a candidate receptor for ASFV26, recent data show that CD163-knockout pigs support GRG infection and exhibit clinical signs consistent with acute infection." (PMID 28860602, 2017). "Flow cytometry analysis found that not only is the CD163+ population more prone to infection with Leishmania parasites but produces more IL-4 and TNF-α than CD163- macrophages." (PMID 28355218, 2017). "In vitro infection of monocyte-derived macrophages and neutrophils with L. infantum and L. amazonensis induces, while BCG reduce the expression of CD163 on macrophage surface Furthermore, presence of sCD163 is reduced during clinical improvements." (PMID 28355218, 2017).
infection (continued). "While CD163 and CD169 macrophages have been explored, other potential mechanisms of transplacental infection of PRRSV have been largely uninvestigated." (PMID 27494990, 2016). "Eight genes (NCF4, CD14, IL17D, CD1D, CD163, IL1R2, TLR9, and TLR2) with different expression in each infection group were selected for qPCR analysis." (PMID 25906258, 2015). "At 24 h post-infection (hpi), adherent pBM cells were processed for flow cytometric analysis with mouse anti VP72 mAb and mouse anti-cell surface marker mAb (CD45, CD163, CD203a, MHCII, CD16)." (PMID 24398227, 2014). "However, over-expression of CD163 and Siglec1 in combination was required for productive infection, indicating a synergistic role for these proteins in ASFV cell entry and infection." (PMID 40692871, 2025). "In this study, the CD163 expression level was increased, while the mRNA level of TWEAK was decreased in the infection group, suggesting that CD163 and TWEAK may be involved in G. parasuis-induced immunosuppression." (PMID 40427615, 2025). "Thus, partial depletion of CD163 was guided by the analysis of the confirmed sites for PRRSV-1 and PRRSV-2 infections." (PMID 39943192, 2025). "Interestingly, both inhibitors also reduced the population of CD163+CD206+ M2 macrophages, measured at the surface level 24-h post-infection." (PMID 41221328, 2025). "PRRSV requires trafficking through CD163-positive early endosomes for productive infection; however, it does not need to traffic through late endosomes." (PMID 40757848, 2025). "We identified 6 hub genes (IL1R1, CD163, TLR5, LY96, MMP9, and IRAK3) and 4 target miRNAs (miR-34a-5p, miR-103-3p, miR-107, and miR-124-3p) that affect the pathophysiological processes of T2DM and CS through ion transport, immune response, and infection." (PMID 40922361, 2025). "Furthermore, the results of immunofluorescence demonstrated that HP-PRRSV activated the necroptosis mainly in CD163+ macrophages, CD3+ T cells, CD19+ B cells, and CD56+ NK cells in the peripheral lymphoid organs during the early infection." (PMID 40143222, 2025). "Levamisole could attenuate the CD163 mRNA expression level and alter the TWEAK mRNA expression level compared to the infection group (p < 0.001)." (PMID 40427615, 2025). "Above all, HP-PRRSV could activate the PKR-mediated-necroptosis in the CD163+ macrophages, CD19+ B cells, CD56+ NK cells, and CD3+ T cells during the initial stages of infection." (PMID 40143222, 2025). "Delta‐infected males showed increased pulmonary infiltration of CD163+ “M2” macrophages, Ly6G+ neutrophils, and NKR‐P1C + NK cells during early onset of infection, and elevated lung inflammatory cytokines such as IL‐10, IL‐6, and IP‐10 than Delta‐infected females." (PMID 40686017, 2025). "Moreover, infection by the B. pertussis (AC+PT−) mutant that produced enzymatically inactive PT toxoid but an active CyaA, reduced CD71 and CD163 expression as much as infection by the wild-type bacteria." (PMID 39078132, 2024). "The CD163 protein, a scavenger receptor cysteine-rich (SRCR) family for hemoglobin clearance, was demonstrated as the most specific and indispensable receptor for PRRSV entry and infection." (PMID 38544785, 2024). "We found that MARV-ZsG-infected cells expressed significantly higher levels of surface CD163 compared to uninfected bystander cells at 1 day post-infection, albeit in the absence of increased sCD163 in cell culture supernatants." (PMID 40295691, 2024). "To investigate whether this phenomenon also occurs in PPMs infected with PRRSV, we assessed the expression of CD163 and CD169 within the PRRSV+ population at 24 h post-infection." (PMID 39723134, 2024). "Following infection with M. bejeranoi, proteins related to the fish immune system were increased, most prominently Scavenger Receptor Cysteine-Rich (SRCR) domain-containing protein (m130/cd163) (fold change 6.12) and pentraxin 3 (fold change 4.38)." (PMID 38891869, 2024).
infection (continued). "We provide evidence that CD163 plays a minor role, unlike those seen in infections with other pathogens, in mediating G. parasuis infection." (PMID 36977274, 2023). "Overall, CD163 expression was significantly downregulated following 24 hr MAP infection for MDMs not treated with vitamin D3 from JD- controls (P <.001), JD+ subclinical (P <.05), and JD+ clinically infected animals (P <.01)." (PMID 36275033, 2022). "However, levels of the M2-type membrane molecules CD163 and CD206 were significantly decreased after infection, and they were further downregulated in the B7-H4 neutralized infected group compared to the infected group." (PMID 36514159, 2022). "The essential scavenger receptor CD163 has been proved to mediate productive infection of PRRSV in various non-permissive cell lines." (PMID 36146862, 2022). "The specificity of CPE was further confirmed by N specific fluorescent signals observed in CD163-3D4/21 cells upon both XJ17-5 and rXJ17-5 PRRSV2 infections, as in MARC-145 cells, indicating the spread of the virions to the neighboring cells and productive infections (third columns)." (PMID 36146862, 2022). "Upon two PRRSV2 infections, CD163-3D4/21, but not non-permissive 3D4/21 cells, expressed viral N proteins detected by Western blotting (top and bottom), and in control MARC-145 cells, the viral N proteins were easily detected by Western blotting (middle)." (PMID 36146862, 2022). "Consistently, both PRRSV2 achieved close infection levels between CD163-3D4/21 and MARC-145 cells, but no detectable infection level in non-permissive 3D4/21 cells." (PMID 36146862, 2022). "Unlike iNOS, the expression of CD163 in the late stage of infection was the highest during the entire infection process." (PMID 36169259, 2022). "Previous studies has shown that CD163 is considered to be a potential ASFV infection receptor, but in subsequent studies it was found that CD163 is not sufficient for the virus to infect host cells." (PMID 35935977, 2022). "Nevertheless, despite this predilection, we observed that infection with the virulent 26544/OG10 downregulated CD163 expression on macrophages, irrespective of the activation status." (PMID 35215110, 2022). "Transfection of non-susceptible cell lines with CD163 renders the cells susceptible to PRRSV infection, while the treatment of PAMs and MARC-145 cells with an anti-CD163 antibody completely blocks the infection." (PMID 36560826, 2022). "Notably, the majority chemokine ligand, which induced cells of the immune system to enter the site of infection, CCL-2, CD80 and CD68 of TAMs, IRF5 and NOS2 of M1, CD163 and MS4A4A of M2 were strongly related to JAK1 expression in LUAD (all P value < 0.0001)." (PMID 34587898, 2021). "The expression level of endogenous CD163 was not affected and the immortalized cells remained permissive for infection with PRRSV-1 and PRRSV-2 strains." (PMID 33916997, 2021). "The last stage is critically dependent on CD163, a scavenger receptor cysteine-rich (SRCR) family for hemoglobin clearance, which is the most specific and indispensable receptor for PRRSV entry and infection both in vitro and in vivo." (PMID 33918746, 2021). "However, when CD163 and ANPEP KO pigs were challenged with PDCoV, resistance to the infection was only limited." (PMID 34696426, 2021). "This suggests that the DEX-induced enhancement of CD163 expression alone is not sufficient to facilitate the infection of IPKM by PRRSV." (PMID 33447967, 2021). "Infection by its etiological agent, PRRS virus (PRRSV), shows a highly restricted tropism of host cells and has been demonstrated to be mediated by an essential scavenger receptor (SR) CD163." (PMID 34193250, 2021). "Furthermore, we investigated the expression of the intracellular signal transducers STAT1/STAT3 and PI3K/AKT, which are engaged in infection-induced signaling via TLR4 and contribute to cytokine- as well as CD163 expression." (PMID 31953452, 2020).